ZNF213-AS1 (ZNF213 antisense RNA 1)
Gene: Long non-coding RNA gene on chromosome 16 (3,100,696 to 3,150,562, reverse strand). Ensembl gene ENSG00000263072.
Gene Ontology:
Biological process: SRP-dependent cotranslational protein targeting to membrane, signal sequence recognition
Cellular component: signal recognition particle, endoplasmic reticulum targeting